S100A9 (S100 calcium binding protein A9)
Diseases named in the same sentence as S100A9 in open-access papers (continued):
Sharing a sentence is not in itself a finding about the gene and the disease.
tumor (continued). "The increased S100A9 expression in our 3D spheroids aligns with previous findings that tumor-infiltrating monocytes/macrophages upregulate S100A9 in cancer cells to promote invasion and migration." (PMID 39193365, 2024). "Previous studies have confirmed the pivotal role of the extracellular secretory proteins S100A8/S100A9 in promoting the proliferation of tumor cells and facilitating invasive metastasis." (PMID 38817853, 2024). "The immunosuppressive microenvironment generated by the contribution of S100A9 supports the metabolic reprogramming of tumor cells and TME cells." (PMID 39195201, 2024). "Further analysis of tumor cross‐sections with enriched neutrophil infiltrations revealed the upregulation of neutrophil‐related genes such as S100a9, Serpine1, Mt2, Nos2, Mt1, IL33, Adm, and Ero1l." (PMID 39113226, 2024). "We found that recombinant S100A9 injection significantly reduced CT26 tumor growth from day 17, compared with untreated controls." (PMID 39497822, 2024). "The association between ESR1 and S100A8 and S100A9 expression levels was positive in Basal patients but negative in Her2, Luminal A, and Luminal B. S100P and S100A14 expression levels were higher in tumor tissues than in normal ones." (PMID 39594999, 2024). "Our research has pinpointed S100A9 macrophages, presenting their capability to enhance angiogenesis via interactions with endothelial cells, thus propelling tumor progression." (PMID 39136841, 2024). "S100A8 and S100A9 mainly induce pro-inflammatory and pro-tumor signaling pathways, and it is hard to explain the correlation with apoptosis in this context." (PMID 39575241, 2024). "S100A8 and S100A9 participate in the regulation of the TME affecting tumor genesis, progression, and metastasis through various pathways." (PMID 39195201, 2024). "ADAM8 has been revealed as one of three potential tumor markers, whereby the others are LYN and S100A9, for metastasis and tumor reoccurrence in colon cancers." (PMID 36910158, 2023). "Our findings also reveal the spatial complexity of myeloid/DC architecture in MM, with some myeloid cell subsets (e.g., cells expressing S100A9) that diffusely infiltrated the marrow but resided predominantly outside tumor lesions." (PMID 37526080, 2023). "All these data support the important role of extracellular S100A8/S100A9 in regulation of the microenvironment and its potential involvement in tumor progression." (PMID 36923707, 2023). "As S100A9 was highly expressed in para-tumor tissues instead of tumor tissues in HCC patients from TCGA database, we suspected that it was mainly produced from cancer stromal cells." (PMID 37133437, 2023). "For this reason, S100A8 and S100A9 can be found in tumor tissues that are infiltrated with immune cells, where they act as chemo-attractants for other immune cells and can promote an inflammatory tumor micro-environment." (PMID 37627239, 2023). "Next, we decided to evaluate the anti-tumor effect of siRNA-mediated S100A9 knockdown (48 h) and venetoclax therapy (24 h) on KG-1a and MOLM-13 cells." (PMID 38110349, 2023). "Subsequent cell necrosis releases S100a9, which promotes immune cells to enter the tumor microenvironment." (PMID 37239383, 2023). "We reveal a yet-unrecognized impact of S100A9 on M1/M2 polarization, in that it contributes to an impaired tumor-migration capacity and increased apoptosis and subsequent longer survival period among patients with MPEs." (PMID 37533789, 2023). "So far, S100A8/S100A9 has been described as a crucial factor for recruitment of MDSCs and immunosuppression in the tumor microenvironment." (PMID 36932197, 2023). "Meantime, S100A9 activates angiogenesis via an autocrine effect on tumor cells and a paracrine effect on stromal cells in oral cancer, similarly accompanied by IL6 production." (PMID 37701037, 2023).
tumor (continued). "Additional macrophage-related markers i.e., Lyve-1 or S100A9 expressed inside the tumor chunks exhibiting loop-like patterns; F4/80+ staining appeared next to PAS+ VM tubes." (PMID 36781833, 2023). "In line with earlier reports, accumulation of immunosuppressive M-MDSCs in tumor passage was further supported by the enhanced expression of S100A8 and S100A9, two calcium binding S100 proteins, associated specifically with M-MDSC." (PMID 38304256, 2023). "S100a9 secreted from tumor cells is an important regulator of the tumor microenvironment and is an endogenous inhibitor of PD-1/PD-L1." (PMID 36810783, 2023). "Single‐cell RNA sequencing has shown the impact of S100A9 as a mediator for promoting cross‐talk between tumour and stroma in metastatic tumours." (PMID 36625080, 2023). "S100A9 expression can be up-regulated by tumor-infiltrating monocytes/macrophages, thus enhancing HCC cell migration and invasion." (PMID 37481543, 2023). "Overall, the downregulation of S100A9 plays a vital role in the process of IL-10 deficiency-mediated MPE suppression by the regulation of M1/M2 polarization, influencing tumor migration capacity, and apoptosis." (PMID 37533789, 2023). "The results showed that S100A8 and S100A9 mRNA increased significantly in tumor compared with normal breast tissue." (PMID 38093319, 2023). "In our experiment, both PDT treatment of Se-PC and PC downregulated the gene expressions of S100a9, Slc2a1, and Lcn2 to slow tumor proliferation by regulating cell metabolism and iron binding." (PMID 37994159, 2023). "Low concentrations of S100A9 promote cell proliferation/survival of both normal intestinal epithelial cells and tumor cells." (PMID 36923707, 2023). "IRF7 inhibited the expression of S100A9, and inhibited the aggregation of granulocyte-like myeloid suppressor cells (G-MDSCs), thus suppressing tumor metastasis." (PMID 37251373, 2023). "To verify this, we compared the mRNA expression of S100A9 in tumor and normal tissues in HCC patients of the ICGC-LIRI-JP project." (PMID 37133437, 2023). "EMMPRIN, also called CD147 or basigin, serves as a receptor for calprotectin in tumor cells and has a higher affinity for S100A9 than that for S100A8." (PMID 37701037, 2023). "In conclusion, S100A9 plays a vital role in the process of IL-10 deficiency-mediated MPE suppression by regulating M1/M2 polarization, thus influencing the tumor-migration capacity and apoptosis." (PMID 37533789, 2023). "Our prognostic signature include four genes, SERPINE2, SNCAIP, NMU, and S100A9, each playing a critical role in tumor progression, invasion, and metastasis." (PMID 37691944, 2023). "Increased expression of S100A9 is considered a sign of increased tumor proliferation and invasive ability and is believed to be a new therapeutic target for cancer treatment." (PMID 37691944, 2023). "In our study, the anti-tumor effect of the doxorubicin/GTN combination was correlated with a decrease in the expression of s100a9 (in tumors) and iNOS (in MDSCs), and with a decrease in PMN-MDSCs immunosuppressive function." (PMID 37370739, 2023). "The GEPIA2 data indicate that both S100A8 and S100A9 were more highly expressed in the tumor issues than in the normal tissues." (PMID 37629174, 2023). "To unravel the potential of S100A9 as a therapeutic target in AML, we evaluated the anti-tumor effect of the clinically available S100A9 inhibitor tasquinimod." (PMID 38110349, 2023). "As immune cells were the main components in cancer stroma, we used the ssGSEA algorithm to examine the relationship between S100A9 gene expression and tumor immune cell infiltration." (PMID 37133437, 2023). "In the tumor array, correlations were observed between S100A9 and S100A8 (R = 0.62), S100A4 (R = 0.78), S100A10 (R = 0.51), S100A12 (R = 0.76), and HMGB1 (R = 0.80)." (PMID 37627239, 2023). "Previous studies have demonstrated that S100A9 play an important role in promoting tumor proliferation, migration, and maintaining cancer stemness." (PMID 37133437, 2023).
tumor (continued). "They detected S100A9 monomers, S100A8/S100A9 heterodimers and S100A9 homodimers intracellularly in spleen cells of tumor bearing animals while only S100A9 monomers and homodimers were secreted." (PMID 35198063, 2022). "It has been proposed that Q-compounds inhibit tumor growth by blocking S100A9 activation of TLR4-mediated inflammation." (PMID 35454108, 2022). "Consistent with above analysis, the S100A9 peptides were identified in all five groups and the number of identified S100A9 peptides were coordinately increased with tumor development stages in Brca1-MT mouse mammary tissues." (PMID 35304461, 2022). "HCC tissues contain both tumor cells and immune cells, with immune cells reported to express S100A9." (PMID 36041055, 2022). "S100A8 and S100A9 are also highly expressed in TME mast cells which promote tumor proliferation and metastasis and indicate poor outcomes according to previous research." (PMID 36148946, 2022). "Consistent with the increased mRNA expression, elevated S100a8/S100a9 protein levels were also observed in MT mammary epithelial cell lines (G600), mammary tissues, and tumor tissues, as revealed by western blot analysis." (PMID 35304461, 2022). "Higher S100A9 levels are associated with higher AFP levels, pathological stages, and larger tumor sizes." (PMID 36041055, 2022). "The optical in vivo imaging of S100A9 in tumor lesions helps in evaluating the tumor–host cell interaction and enables the estimation of the individual malignant potential." (PMID 35741108, 2022). "S100A8/S100A9 proteins released by phagocytes also contributed to the early recurrence of cancer and tumor invasion." (PMID 35741108, 2022). "Of note, it was shown that S100A9 activates NK cells through binding to its cognate receptor RAGE to inhibit tumor growth." (PMID 35304461, 2022). "Altogether, these data uncovered an important role of S100a9-Cxcl12 in inducing MDSCs accumulation to establish an immunosuppressive/tumor-permissive environment." (PMID 35304461, 2022). "For example, interleukin (IL)-6 and IL-8 released from myofibroblasts in the tumor microenvironment induce myeloid cells to differentiate into S100A8/S100A9-expressing myeloid-derived suppressor cells and M2 macrophages." (PMID 35177036, 2022). "Neutrophil-derived MDSCs, in turn, release S100A8 and S100A9 to sustain tumor angiogenesis and to create a pre-metastatic niche by facilitating the extravasation and growth of metastasis-initiating cells." (PMID 36303837, 2022). "Increased MDSCs were observed by S100A9 staining in the primary tumor and the lung of 628 mice and sgATP11b/OE-Ptdss2-628 mice compared with control mice (WT-Ctr)." (PMID 35025764, 2022). "It was recently reported that S100A4 enhanced the expression of mouse SAA1 and SAA3, which stimulated expression of RANTES, G-CSF, MMP2, S100A8, and S100A9 to promote tumor metastasis." (PMID 35936690, 2022). "S100A9 is a DAMP molecule that can amplify inflammation in the tumor microenvironment and lead to malignancy progression." (PMID 35560794, 2022). "Recent studies have shown the presence of S100A9 and inflammatory factors in the tumor microenvironment." (PMID 35123499, 2022). "These scores all increased in high-expression group of COLEC12, TREM1 and S100A9, while the corresponding tumor purity decreased, which further confirmed the roles of these IRGs in regulating tumor microenvironment." (PMID 36685822, 2022). "Pro-angiogenic factors that are released by neutrophils, such as VEGF, Bv8, MMP-9, and S100A8/S100A9, directly induce tumor angiogenesis via the activation of endothelial cell proliferation." (PMID 35158807, 2022). "Although the infiltration of MDSCs expressing S100A8 and S100A9 has been closely related to tumor stage, lymph node metastases, and poor prognosis, there is a rising evidence that CD147+ myeloid cells are key players in HPV-driven cancers." (PMID 36303837, 2022).
tumor (continued). "Overexpression of S100A9 enhanced the metastatic ability of tumor cells, even after neutralizing CD11b‐positive cells in a C57 mouse model, as measured by in vivo bioluminescent imaging." (PMID 36041055, 2022). "S100A9-expressing MDSC were also discovered as essential contributors in facilitating tumor dissemination in a melanoma and lung carcinoma mouse model and are regarded as the most aggressive tumor promoters." (PMID 35103216, 2022). "Several studies on different types of cancer cells have shown that S100A9 induces activation of NF-kB, and that knockdown of S100A9 expression decreases tumor invasion." (PMID 34374812, 2022). "There is an increasing evidence for distinct functions of S100A8 and S100A9 if expressed as intracellular and extracellular by tumor or immune cells." (PMID 36303837, 2022). "S100a8 and S100a9 enhance the immunosuppressive activity of neutrophils and recruit immature myeloid cells to the tumor." (PMID 34070438, 2021). "Within the whole tumor slices, S100A9-positive cells (stained brown) correlated with the CNR determined for the therapy groups via FRI." (PMID 33401528, 2021). "All these findings indicate that tumor exosomes containing S100A8 and S100A9 proteins suppresses DCs maturation and improves the premetastatic niche formation in tumor-draining lymph nodes." (PMID 34078376, 2021). "S100A9, a member of the S100 family, is expressed in granulocytes, monocytes, macrophages, MDSCs and tumor cells in various cancers." (PMID 34157683, 2021). "Among the dysregulated proteins, S100A9 was confirmed to be elevated in both serums and tumor stroma from NKTCL patients." (PMID 34045609, 2021). "The expression levels of S100A8 and S100A9 were elevated in serum and tumor tissue samples from HCC patients." (PMID 34517344, 2021). "Compared with para-cancer tissues, the expression levels of S100A4/S100A6/S100A10/S100A11/S100A13/S100A14/S100P were higher in HCC tissues, while the expression levels of S100A8/S100A9/S100A12 were decreased in tumor tissues." (PMID 33815482, 2021). "S100A9 is expressed in and secreted by immune cells in the pre‐metastatic niche, as well as, post‐tumor development, therefore making it a suitable targeted for prophylaxis and therapy." (PMID 34519180, 2021). "S100A9 levels are found to elevated in tumor tissue and peripheral blood of patients with colorectal cancer (CRC), which is capable of promoting MDSC chemotaxis and activation in RAGE-mediated p38/MAPK and TLR4-mediated NF-κB pathways." (PMID 34689842, 2021). "S100A9 was overexpressed in both serum and tumor tissue from NKTCL patients compared with healthy individuals." (PMID 34045609, 2021). "With S100A8/S100A9 as an important mediator in the TME, this study can pave the way for an imaging biomarker development for modern tumor therapy and ultimately underline its translational potential." (PMID 33401528, 2021). "Inhibition of ERK1/2 signaling significantly decreased tumor growth and PD-L1 expression induced by S100A9." (PMID 34045609, 2021). "By binding its main TLR4 and RAGE receptors, S100A9 participated in regulating inflammatory-immune response and tumor progression." (PMID 34093546, 2021). "For example, S100A9 acts as a potent amplifier of inflammation in cancer progression as well as tumor spread and has been reported to strongly upregulate in many tumors." (PMID 34650925, 2021). "In this study, mice were first inoculated with B16F10 or 4T1‐Luc tumor cells, followed by the treatment with S100A9‐targeted CPMV." (PMID 34519180, 2021). "Even though an association between the S100A8-S100A9 and TGF-β signaling pathway has been established, it is not fully understood how S100A8 and S100A9 promote tumor development." (PMID 34201758, 2021). "Collectively, our findings indicated that the primary S100A9-expressing cells in adjacent nontumoral tissue are CD15+ neutrophils, and both CD68+ Mφs and CD15+ neutrophils highly express S100A9 in HCC tumor tissues." (PMID 34157683, 2021).
tumor (continued). "To investigate the relationship between S100A9 expression and the immune system, we adopted the CIBERSORT algorithm to evaluate the association between S100A9 gene expression and tumor immune cell infiltration using the TCGA-LIHC data set." (PMID 34157683, 2021). "The roles of S100A8 and S100A9 have been studied in many tumor models (colon, breast, neuroblastoma, etc.)and seems to be dual." (PMID 33801279, 2021). "Previously, tumor-infiltrating S100A9-positive inflammatory or immune cell tissues were closely related to the pathological stage of CRC." (PMID 34093546, 2021). "Among the five DEIGs, S100A9 is involved in cell growth, differentiation, and apoptosis and promotes tumor metastasis." (PMID 34401208, 2021). "Among the upregulated proteins, S100A9, an immune-related molecule, has been reported to play a key role in tumor progression and immune escape." (PMID 34045609, 2021). "Compared with the normal mice group, lung section from tumor-bearing mice exhibited enhanced S100A9 and MMP-9 expression on the 14th day." (PMID 34045459, 2021). "Low concentration of S100A8/S100A9 promotes tumor growth via a RAGE-dependent mechanism that involves the activation of MAPK and NFκB signaling pathways." (PMID 34572138, 2021). "These are in agreement with the earlier studies indicating that the higher level of S100A9 in the TME is, in part, responsible for the tumor-associated dendritic cells (TADCs)-mediated chemoresistance of breast cancer." (PMID 34078376, 2021). "Further study we will employ S100A9 knockout mice to examine the function of S100A9 in immunosuppressive microenvironment during tumor growth of NKTCL." (PMID 34045609, 2021). "When administered prior to tumor challenge, S100A9‐targeted CPMV treatment allows local immunomodulation of innate immune cells and subsequent rejection of tumor cells in lung (prophylaxis)." (PMID 34519180, 2021). "S100A9 supports proliferation and metastasis in other tumor types; S100A9, hemopexin, and inter-alpha-trypsin inhibitor heavy chain H4 (ITIH4) were identified in saliva of patients with RCC and were suggested as potential biomarkers for disease screening." (PMID 34572331, 2021). "Proinflammatory S100A8 and S100A9, whose expression is induced by factors secreted from primary tumours such as TNF-α, TGF-β and VEGF-A, serve as recruiters of CD11b+ myeloid cells into the pre-metastatic lungs, in turn promoting metastasis formation." (PMID 35006432, 2021). "S100A9 is prevalently reported to have significant roles in multiple processes of MDSC involved activity in tumor context, including MDSC recruitment, MDSC induced tumorigenesis and tumor progression." (PMID 34689842, 2021). "The effect of calprotectin on tumor cells is dependent on the concentration: at high concentrations, the heterocomplex of S100A8/S100A9 exerts an apoptotic effect, but at low concentrations, calprotectin promotes tumor cell growth." (PMID 33466593, 2021). "Previous studies have unveiled that 10μg/mL recombinant human S100A9 protein promoted tumor development." (PMID 33203795, 2020). "Reassuringly, several known CRC biomarkers, such as S100A9 and Tenascin-C, were found to be overexpressed in the tumor tissues by our mass spectrometric approach." (PMID 32166002, 2020). "Tasquinimod (ABR-215050), an oral immunomodulatory compound, reportedly affects the accumulation and function of tumor-suppressive myeloid cells, MDSCs, and M2-like TAMs via targeting the inflammatory protein S100A9." (PMID 32824865, 2020). "Knock down of S100A9 diminished tumor proliferation and invasion through the inhibition of MAPK, NF-kappa B and AKT1." (PMID 33203795, 2020). "AKT1 plays a vital role in S100A9 downstream signal transduction pathway in favor of tumor progression, including PA." (PMID 33203795, 2020).